FIS1 (fission, mitochondrial 1)
Diseases named in the same sentence as FIS1 in open-access papers (continued):
Sharing a sentence is not in itself a finding about the gene and the disease.
Cachexia (3 papers, 2012 to 2021). Severe weight loss, wasting of muscle, loss of appetite, and general debility related to a chronic disease. "Circulating IL-6 is a driver of muscle wasting in the ApcMin/+ mouse model of cancer cachexia, and cachexia is accompanied by altered mitochondrial dynamics and increased FIS-1 protein expression." (PMID 30918582, 2019). "Here we show FIS1 was only increased during later stages of cachexia, which coincided with the induction of pro-apoptotic Bax mRNA expression, which further suggests an association between mitochondrial fission and apoptosis." (PMID 22769563, 2012). "The loss of mitochondria is preceded by the reduction in PGC-1α and mitochondrial fusion proteins Mfn1 and 2 during the initial stages of cachexia, while the induction of fission protein FIS1 occurs with the progression of cachexia." (PMID 22769563, 2012). "This antibody also suppressed the IL-6 activation of muscle STAT3 and FIS-1 protein expression during cachexia, suggesting that the intracellular IL-6 signaling targets such as STAT3 may contribute to the regulation of mitochondrial fission." (PMID 30918582, 2019). "Related to the regulation of mitochondrial fission, our data show an increase in muscle FIS1 protein expression in the later stages of cachexia, which could also be induced by systemic over-expression of IL-6." (PMID 22769563, 2012). "IL-6 receptor antibody administration after the onset of cachexia improved mitochondrial content, PGC-1α, Mfn1/Mfn2 and FIS1 protein expression." (PMID 22769563, 2012).
colitis (3 papers, 2021 to 2025). Inflammation of the colon. "Interestingly, experimental studies suggest that excessive mitochondria fragmentation may promote the inflammation of intestinal epithelial cells and inhibition of FIS1 protein can prevent colitis by maintaining enterocyte and macrophage mitochondrial networks." (PMID 38103512, 2023). "However, both Fis1 and Mfn1 were not effectively upregulated in KOIEC mice during DSS-induced colitis." (PMID 40089459, 2025).
colorectal carcinoma (3 papers, 2023). A malignant epithelial neoplasm that arises from the colon or rectum and invades through the muscularis mucosa into the submucosa. "To investigate the role of the SKY insert on cellular functions, we transiently expressed WT and FIS1 variants along with mitochondrially targeted YFP in human colorectal carcinoma (HCT116) cells." (PMID 37777154, 2023).
Depression (3 papers, 2022 to 2025). "We also examined the effects of EA on neuronal mitochondrial fragmentation and the SENP3/FIS1 pathway, thereby providing new insights into the mechanisms of action of EA in depression treatment." (PMID 41551190, 2025). "SUMO is a post-translational modification of FIS1 and is also involved in the pathogenesis of depression." (PMID 41551190, 2025).
glioma (3 papers, 2022 to 2025). A benign or malignant brain and spinal cord tumor that arises from glial cells (astrocytes, oligodendrocytes, ependymal cells). "In glioma models, enhanced radiation sensitivity correlates with fission amplification where Fis1 inhibition alleviates mitochondrial apoptosis." (PMID 41331010, 2025).
ischemia (3 papers, 2018 to 2025). A hypoperfusion of the BLOOD through an organ or tissue caused by a PATHOLOGIC CONSTRICTION or obstruction of its BLOOD VESSELS, or an absence of BLOOD CIRCULATION. "Blocking the interaction between Drp1 and Fis1 with P110 also preserves mitochondrial morphology and cellular function in rat cardiac myocytes under ischemia-reperfusion injury in vitro and ex vivo and improves LV function in an ischemia-reperfusion injury model in vivo." (PMID 30042687, 2018).
melanoma (3 papers, 2021 to 2022). A malignant, usually aggressive tumor composed of atypical, neoplastic melanocytes. "In cutaneous melanoma both FIS1 and MFN2 protein expression correlated with a higher Clark level—a staging measure of how deep melanoma has invaded in the skin." (PMID 35356277, 2022). "Further studies will need to be performed to determine mechanistically why certain melanoma subtypes may rely more on MFN2 as opposed to FIS1." (PMID 35356277, 2022).
amyotrophic lateral sclerosis (2 papers, 2018 to 2021). Amyotrophic lateral sclerosis (ALS) is a neurodegenerative disease characterized by progressive muscular paralysis reflecting degeneration of motor neurons in the primary motor cortex, corticospinal tracts, brainstem and spinal cord. "A study also reported that the C9ORF72 gene, the mutation of which causes amyotrophic lateral sclerosis, has a strong and lethal genetic interaction with Fis1." (PMID 34061429, 2021).
cardiomyopathy (2 papers, 2020 to 2021). A disease of the heart muscle or myocardium proper. "Hence, METH-induced decreased Sigmar1 expression underlies the alteration in CREB/pCEBSer133/Fis1 signaling that adversely affects mitochondrial dynamics, morphometry, and respiration in cardiomyocytes, providing evidence for a pathogenic molecular mechanism in METH-induced cardiomyopathy." (PMID 33203971, 2020).
diabetic kidney disease (2 papers, 2021 to 2024). Progressive kidney disorder caused by vascular damage to the glomerular capillaries, in patients with diabetes mellitus. "They find that miR-379 knockout mice are protected from diabetic kidney disease by enhancing mitophagy via FIS1, suggesting miR-379 as a potential therapeutic target for diabetic kidney disease." (PMID 33398021, 2021).
diabetic retinopathy (2 papers, 2020 to 2022). "The results from the current study have shed light on the relative contributory role of Drp1 and Fis1 in mitochondrial fragmentation related to vascular cell loss in diabetic retinopathy." (PMID 32664237, 2020). "In the same diabetic retinopathy donors, Fis1 expression was also significantly higher." (PMID 35399705, 2022).
dyslipidemia (2 papers, 2022 to 2025).
endothelial dysfunction (2 papers, 2024 to 2025). In vascular diseases, endothelial dysfunction is a systemic pathological state of the endothelium (the inner lining of blood vessels) and can be broadly defined as an imbalance between vasodilating and vasoconstricting substances produced by (or acting on) the endothelium. "Silencing Fis1 accelerates the switching to STX17‐mediated mitophagy, worsening endothelial dysfunction, whereas Fis1 overexpression prevents this switching, reducing ROS and apoptosis and enhancing eNOS phosphorylation." (PMID 40135829, 2025). "The same senescent phenotype was induced by FIS1 silencing in young (low-passage) ECFCs, which demonstrate reduced proliferation activity, denoting the role of FIS1 in mitochondrial and endothelial dysfunction in an aging model." (PMID 38392289, 2024).
Hypercalcemia (2 papers, 2022). An abnormally increased calcium concentration in the blood. "CKD mice were treated with Calcitonin to alleviate hypercalcemia to verify whether Drp1/Fis1-mediated mitochondrial fragmentation involved in neuronal damage caused by CKD-induced hypercalcemia." (PMID 36050772, 2022). "Calcitonin suppressed Drp1/Fis1-mediated mitochondrial fragmentation to attenuate hypercalcemia-induced neuronal injury after CKD." (PMID 36050772, 2022). "Our findings were consistent with these findings and additionally added evidence suggesting that suppression of Drp1/Fis1-mediated mitochondrial fragmentation attenuated hypercalcemia-induced neuronal injury following CKD." (PMID 36050772, 2022). "The obtained data indicated that hypercalcemia aggravated neuronal damage via Drp1/Fis1-mediated mitochondrial fragmentation in CKD." (PMID 36050772, 2022). "It is possible that hypercalcemia may induce the expression of Drp1 and Fis1 by regulating key factors such as CaMKII, PP2A regulatory subunit Bβ2, CDK5, and calcineurin, which shall be excavated in the following experiments." (PMID 36050772, 2022).
liver cancer (2 papers, 2021 to 2024). An epithelial or non-epithelial malignant neoplasm that arises from the liver. "We identified YWHAE as significantly associated with liver fibrosis, AVIL, FIS1, MUC1, ACOT7, CLUH, HNF4A, and TNFSF10 with liver cancer, and AVIL with liver disease-related mortality (FDR-adjusted P values < 0.05)." (PMID 38862964, 2024). "We elucidated for the first time the biological significance of Met in regulating the phosphorylation of Y38 of Fis1 in metastatic liver cancer cells, providing a new predictor for the relapse and prognosis of patients with liver cancer." (PMID 34848680, 2021).
lung adenocarcinoma (2 papers, 2018 to 2021). A carcinoma that arises from the lung and is characterized by the presence of malignant glandular epithelial cells. "We found that the expression of FIS1 was lower in stage I lung adenocarcinoma compared to that of stage II/III/IV lung adenocarcinoma." (PMID 34051059, 2021). "During our characterization of mitophagic activities in lung adenocarcinoma A549‐SD CSCs, we observed augmentation of stemness by mitophagy and the elevated expression of FIS1." (PMID 34051059, 2021). "In addition, we assessed the clinical relevance of FIS1 in lung adenocarcinoma using The Cancer Genome Atlas database." (PMID 34051059, 2021).
pulmonary arterial hypertension (2 papers, 2023 to 2025). Pulmonary arterial hypertension (PAH) is a group of diseases characterized by mean pulmonary artery pressure >20 mmHg and elevated pulmonary arterial resistance leading to right heart failure. "In a model of pulmonary arterial hypertension constructed in mice with chronic hypoxia, the FIS1 deSUMOylation-SUMOylation transition in pulmonary endothelium is an intrinsic pathogenesis of hypoxic PH." (PMID 39984463, 2025).
Stroke (2 papers, 2020 to 2022). Sudden impairment of blood flow to a part of the brain due to occlusion or rupture of an artery to the brain. "It is reported that selective inhibition of Drp1/Fis1 interaction with Hep as a Drp1–Fis1 peptide inhibitor P110 reduced pathological mitochondrial fission, preserved cell survival and improved ATP production in a stroke model." (PMID 35606779, 2022). "At the time of stroke, rats treated with LV-UCP2 still showed a large UCP2 upregulation in the striatum, associated with increases in OPA1 and FIS1 protein levels, and reductions in PGC1-α, SOD2, TNFα mRNA levels and NRF2 protein levels." (PMID 32560241, 2020). "Therefore, we first explored whether EXO-Hep inhibited Drp1/Fis1-mediated stroke-induced astrocytic activation and improved the secretion of healthy mitochondria." (PMID 35606779, 2022).
tongue squamous cell carcinoma (2 papers, 2017 to 2018). A squamous cell carcinoma that arises from the tongue. "Conversely, it is also upregulated in patients with non-metastatic prostate cancer and plays a role in cisplatin resistance in tongue squamous cell carcinoma with cisplatin sensitivity being restored upon knockdown of FIS1." (PMID 30404157, 2018).
age (1 paper, 2019). A temporal measurement of the time period elapsed since an identifiable point in the life cycle of an organism. "Fis1, the mitochondrial fission regulator, is also associated with age-related neurodegeneration, and has been observed to be increased in AD and HD patient tissues." (PMID 31105084, 2019).
Barrett esophagus (1 paper, 2018). Esophageal lesion lined with columnar metaplastic epithelium which is flat or villiform. "Based on previous studies investigating the role of BAK1, FIS1, and SFN, one primary function of these three genes in Barrett’s esophagus and in Barrett’s associated OAC may also be in conferring therapeutic resistance to cells; however, further studies are necessary to explore this relationship." (PMID 30404157, 2018). "It is also speculated that increased levels of FIS1 promotes mitophagy to eliminate defective mitochondria following cellular stress and perhaps supports functional oxidative phosphorylation known to be associated with progression to OAC in Barrett’s esophagus." (PMID 30404157, 2018).
cognitive decline (1 paper, 2018). "This suggests that Drp1/Fis1 interaction and excessive mitochondrial fission greatly contribute to Aβ-mediated and AD-related neuropathology and cognitive decline." (PMID 29464060, 2018).
COVID-19 (1 paper, 2021). A disease caused by infection with severe acute respiratory syndrome coronavirus 2. "Similarly, COVID-19 symptomatic cases also showed significantly lower expression levels of these genes compared to controls, together with a decrease in genes belonging to the mitochondrial respiratory chain subunits (NDUFA9, SDHA, COX4I1) and to mitochondrial dynamics (DNM1L, FIS1)." (PMID 34679654, 2021).
cyst (1 paper, 2018). A sac-like closed membranous structure that may be empty or contain fluid or amorphous material. "In immunofluorescence analysis, anti-Eg-Fis1 and anti-Eg-PDCD6 rabbit IgGs were applied for detection of their respective native proteins in adult worms, cyst walls (from fertile and infertile cysts), and PSCs in E. granulosus." (PMID 30205566, 2018).
dominant optic atrophy (1 paper, 2022). "The Drp1-binding mutant Mid51(Y240N) linked to dominant optic atrophy was still able to interact with WT Fis1 in a Mid51(Y240N)/Fis1 complex." (PMID 36044022, 2022). "In contrast, mutant Mid51(Y240N) associated with dominant optic atrophy, which does not disrupt Mid51/Fis1-coupled oligomerization, does not misregulate lysosomal untethering events or downstream lysosomal network dynamics." (PMID 36044022, 2022). "Mutant Mid51(Y240N) was recently linked to dominant optic atrophy and is located in Mid51’s Drp1-binding region, which led to defective mitochondrial fission/fusion dynamics that are dependent on Drp1 GTP hydrolysis, but normal Mid51/Fis1 oligomerization and lysosomal networks." (PMID 36044022, 2022).
emphysema (1 paper, 2022). "The degree of impaired mitochondrial fission/fusion as suggested by reduced expression of mitofusin 1 (MFN1), optic atrophy 1 (OPA1), Fission, Mitochondrial 1 (FIS1) and phosphorylated dynamin-related protein 1 (p-DRP1) correlated with level of emphysema." (PMID 35820851, 2022).
endotoxemia (1 paper, 2024). "During lipopolysaccharide-stimulated endotoxemia, activated DNA-PKcs induced mitochondrial fission via mitochondrial fission 1 protein (Fis1) 23, suggesting that DNA-PKcs activation is associated with mitochondrial abnormalities." (PMID 38389837, 2024).
fluorosis (1 paper, 2025). "Mfn1 protein and mRNA expression was evidently decreased in the renal tissues of rats with chronic fluorosis, but Fis1 expression was increased." (PMID 39896143, 2025).
focal segmental glomerulosclerosis (1 paper, 2025). A renal disorder characterized by sclerotic lesions in the glomeruli. "It has been reported that FIS1 expression is significantly reduced in patients with focal segmental glomerulosclerosis, lupus nephritis, and CKD." (PMID 40722880, 2025).
Glucose intolerance (1 paper, 2022). Glucose intolerance (GI) can be defined as dysglycemia that comprises both prediabetes and diabetes. "Fis1 activity is also inversely correlated with glucose intolerance induced by HFD feeding." (PMID 35015731, 2022).
HCMV infection (1 paper, 2022). "The results showed that the expression of genes regulating mitochondrial fusion (MFN1 and MFN2) was decreased after HCMV infection, while the expression of genes regulating mitochondrial division (Drp1 and FIS1) was upregulated." (PMID 35359726, 2022).
Hypercholesterolemia (1 paper, 2022). An increased concentration of cholesterol in the blood.
hyperuricemia (1 paper, 2025). An abnormally high level of uric acid. "To investigate the mechanisms of hyperuricemia-related cardiovascular diseases, we examined the expression of mitochondrial fission 1 protein (FIS1), as well as mitofusin 1 (MFN1) and mitofusin 2 (MFN2), which are key regulators of mitochondrial fusion." (PMID 40361044, 2025).
Infertility (1 paper, 2018). "Since apoptosis induced by oxidative stress is one of the mechanisms causing infertility of hydatid cysts, further studies will be carried out to evaluate whether Eg-Fis1 is involved in regulating the production of infertile cysts." (PMID 30205566, 2018).
insulinoma (1 paper, 2013). "Indeed, downregulation of the fission protein Fis1 attenuated mitophagy and significantly decreased GSIS in rat insulinoma cells." (PMID 23565276, 2013).
kidney damage (1 paper, 2023). "Results suggested that the catalytic subunit of DNA-dependent protein kinase (DNA-PKcs) can interact with Fis1, and phosphorylate its Thr34 site, which promotes the binding of Fis1 and Drp1, thereby exacerbating kidney damage induced by AKI." (PMID 37635869, 2023).
malaria (1 paper, 2020). Malaria is a serious and sometimes fatal disease caused by a parasite that commonly infects a certain type of mosquito which feeds on humans. "However, it has remained unknown whether Fis1 is essential for mitochondrial fission in malaria parasites." (PMID 32968006, 2020). "Our Fis1 KO data in malaria parasites are consistent with the idea of the nonessentiality of Fis1 proposed by KD approaches carried out in Toxoplasma gondii." (PMID 32968006, 2020).
migraine (1 paper, 2025). "When mitochondrial dynamics are examined, migraine models frequently exhibit the upregulation of fission-related genes such as Drp1 and Fis1, along with the downregulation of fusion-related genes like Mfn1." (PMID 40868921, 2025).
non-alcoholic fatty liver disease (1 paper, 2025). "In non-alcoholic fatty liver disease (NAFLD), abnormal lipid accumulation leads to impaired mitophagy and altered levels of Drp1 and Fis1 proteins." (PMID 39796234, 2025).
non-alcoholic steatohepatitis (1 paper, 2022). "In a western diet-induced non-alcoholic steatohepatitis (NASH) mouse model, Drp1, Fis1 and Mfn2 expression was reduced." (PMID 35933403, 2022).
oncocytic tumors (1 paper, 2025). "Notably, MFN2, OPA1, DRP1, and FIS1 have been found to be overexpressed in oncocytic tumors, independent of mitochondrial content." (PMID 40485730, 2025).
osteoarthritis (1 paper, 2025). A noninflammatory degenerative joint disease occurring chiefly in older persons, characterized by degeneration of the articular cartilage, hypertrophy of bone at the margins and changes in the synovial membrane. "While no patients with a mutation in the fis1 gene have yet been reported, FIS1 is significantly suppressed in human osteoarthritis (OA) chondrocytes." (PMID 39851575, 2025).
ovarian carcinoma (1 paper, 2022). A malignant neoplasm originating from the surface ovarian epithelium. "In our experiments, we found that the expression of DRP1 and Fis1 expression was reduced in mice ovaries after CP treatment, which was consistent with previous studies that CP exerts its adverse effects on the human ovarian cancer SKOV3 cells through mitochondrial dynamics-related proteins." (PMID 36555999, 2022).
overnutrition (1 paper, 2022). An imbalanced nutritional status resulting from excessive intake of nutrients. "Collectively, these studies indicate that the Fis1-Atf5 axis of the mitochondrial IRS protects against overnutrition-induced metabolic dysregulation." (PMID 35015731, 2022). "In addition, reduced Fis1 activity by Ad-shFis1 in the liver of mice after a 4-week HFD feeding reduced glucose tolerance, indicating that defective mitophagy/increased oxidative stress may cause metabolic dysfunction during the course of chronic overnutrition." (PMID 35015731, 2022). "As such, the Fis1-Atf5 axis of the ISR may provide a therapeutic target to disrupt a detrimental feedback loop of oxidative damage, defective mitophagy, and IFN-I–induced metabolic inflammation in overnutrition." (PMID 35015731, 2022).